H1-4 (H1.4 linker histone, cluster member)
Description:
Histone H1 protein binds to linker DNA between nucleosomes forming the macromolecular structure known as the chromatin fiber. Histones H1 are necessary for the condensation of nucleosome chains into higher-order structured fibers and promote formation of the H3K27me3 mark by the PRC2/EED-EZH2 complex. Ability to associate with nucleosomes and compact chromatin depends on linker DNA length and trajectory. Also acts as a regulator of individual gene transcription through chromatin remodeling, nucleosome spacing and DNA methylation.
Synonyms: H1F4; HIST1H1E; H1.4; H1e; H1s-4; RMNS; dJ221C16.5
Tractability: Small molecule: a structure with a bound ligand is known. PROTAC: ubiquitination databases record sites on it.
Gene: Protein-coding gene on chromosome 6 (26,156,329 to 26,157,115, forward strand). Ensembl gene ENSG00000168298.
Subcellular location: Nucleus; Chromosome
Subcellular location (Human Protein Atlas): Nuclear speckles; Cytosol
Pathways (Reactome):
Cellular responses to stimuli: Formation of Senescence-Associated Heterochromatin Foci (SAHF)
Programmed Cell Death: Apoptosis induced DNA fragmentation
Gene Ontology:
Molecular function: chromatin DNA binding; histone deacetylase binding; protein binding; RNA binding; structural constituent of chromatin; double-stranded DNA binding; nucleosomal DNA binding; DNA binding
Biological process: chromosome condensation; negative regulation of DNA recombination; nucleosome assembly
Cellular component: chromosome; heterochromatin; nuclear speck; nucleus; euchromatin; chromatin; nucleosome
Genetic constraint (gnomAD): Loss-of-function variants: 9 observed, 7.48 expected, observed/expected ratio (o/e) 1.2, 90% interval 0.71 to 1.85. That is too few expected variants to judge how well the gene tolerates losing a copy. Missense variants: 646 observed, 297.85 expected, observed/expected ratio (o/e) 2.17. Synonymous variants: 318 observed, 135.79 expected, observed/expected ratio (o/e) 2.34.
Gene-disease validity (ClinGen):
ClinGen rates the evidence that H1-4 causes each of these diseases.
syndromic intellectual disability (autosomal dominant): Definitive. A intellectual disability that is part of a larger syndrome.
Homologues: Orthologues: chimpanzee H1-4 (100% identical), macaque H1-4 (99% identical), dog H1-4 (97% identical), rabbit H1-4 (97% identical), mouse H1f4 (94% identical), rat H1f4 (91% identical), zebrafish si:dkey-23a13.9 (65% identical), zebrafish h1l1 (63% identical), Caenorhabditis elegans hil-3 (27% identical), Caenorhabditis elegans hil-4 (26% identical), Caenorhabditis elegans hil-6 (25% identical), Caenorhabditis elegans hil-2 (24% identical), and 1 more. Paralogues in human: H1-5 (88% identical), H1-3 (87% identical), H1-2 (85% identical), H1-1 (72% identical), H1-6 (52% identical), H1-0 (42% identical), H1-8 (35% identical), H1-10 (29% identical), H1-7 (26% identical).
Diseases named in the same sentence as H1-4 in open-access papers:
H1-4 is named in the same sentence as 27 diseases in open-access papers, as found by Europe PMC text mining. Sharing a sentence is not in itself a finding about the gene and the disease. The quoted sentences say what the papers report.
lymphoma (1 paper, 2024). A malignant (clonal) proliferation of B- lymphocytes or T- lymphocytes which involves the lymph nodes, bone marrow and/or extranodal sites. "Indeed, many recent studies have indicated the pathogenic relevance of histone H1-4 mutations in cancers and their high recurrences in particular cancer types such as lymphomas." (PMID 38329268, 2024).
pemphigus (1 paper, 2025). Pemphigus is a group of rare autoimmune diseases that cause blistering of the skin and mucous membranes (mouth, nose, throat, eyes, and genitals).This conditioncan occur at any age, but often strikes people in middle or older age. "Differential expression analysis was conducted to investigate the expression patterns of the five genes (XBP1, FBXO45, SAT2, AIFM1, and ACSL4) and eight other DEGs associated with ferroptosis (G3BP1, WBP11, TET2, IRF8, FASN, GDPD5, H1-4, and HUWE1) in both the pemphigus and control groups." (PMID 40612574, 2025).
H1-4 also shares sentences with these, for which no sentence is quoted: tumor (10 papers); cancer (6); myeloma (3); Rahman syndrome (3); autism (2); breast carcinoma (2); esophageal cancer (2); infection (2); neurodevelopmental disorder (2); schizophrenia (2); B-cell lymphomas (1); benign tumor (1); cognitive decline (1); colorectal cancer (1); follicular lymphoma (1); glioblastoma (1); hepatocellular carcinoma (1); Intellectual disability (1); lung carcinoma (1); melanoma (1); multiple myeloma (1); osteosarcoma (1); overgrowth syndrome (1); pancreatic cancer (1); prostate carcinoma (1).